MRPL13 (mitochondrial ribosomal protein L13)
Diseases named in the same sentence as MRPL13 in open-access papers (continued):
Sharing a sentence is not in itself a finding about the gene and the disease.
lung adenocarcinoma (3 papers, 2023 to 2025). A carcinoma that arises from the lung and is characterized by the presence of malignant glandular epithelial cells. "This study found that MRPL13 is highly expressed in lung adenocarcinoma and is associated with poor prognosis." (PMID 37946181, 2023). "In lung adenocarcinoma, single-cell analysis and in vitro experiments have demonstrated that MRPL13 knockdown decreases cell viability, delays tumor proliferation and invasion, and increases apoptosis." (PMID 40841355, 2025). "Further experimental validation showed that MRPL13 in lung adenocarcinoma tissue is higher than that in corresponding normal tissue in many aspects (RNA or protein)." (PMID 37827692, 2023). "Our findings demonstrate that MRPL13 knockout negatively impacted the cell activity, proliferation, periodic differentiation, apoptosis, migration, and invasion of lung adenocarcinoma cells." (PMID 37827692, 2023). "Knockdown of MRPL13 in lung adenocarcinoma inhibited cancer cell survival, delayed tumor division, reduced metastasis, and increased cancer cell apoptosis." (PMID 37827692, 2023). "Real-time fluorescence quantitative PCR was employed to examine the expression of 20 clinical samples of lung adenocarcinoma, confirming once more that compared with the normal tissue group, the expression of MRPL13 in the LUAD group was higher." (PMID 37827692, 2023). "The low expression group of MRPL13 in lung adenocarcinoma showed higher levels of CD8+ T cells, B cells, NK cells, and macrophages." (PMID 37827692, 2023). "Therefore, we tried to clarify the relationship between MRPL13 and pan-cancer, and verified it in lung adenocarcinoma by various methods." (PMID 37827692, 2023). "In this study, the GPSAdb database was employed to identify the upstream gene FOXM1, which may induce changes in MRPL13 expression after knockout in lung adenocarcinoma cell lines." (PMID 37827692, 2023). "We began by investigating whether MRPL13 functions as a tumor-promoting factor in lung adenocarcinoma." (PMID 37827692, 2023). "Therefore, we believe that targeting MRPL13 is an important part of anti-lung adenocarcinoma pharmacological therapy." (PMID 37827692, 2023). "MRPL13 knockdown inhibits the proliferation of lung adenocarcinoma cells." (PMID 37827692, 2023). "In conclusion, MRPL13 could be a potential predictive biomarker for immunotherapy of malignant tumors, including lung adenocarcinoma (LUAD)." (PMID 37827692, 2023). "However, the systematic study of the role of MRPL13 in the promotion of cancer occurrence, progression, metastasis, and prognosis, from pan-cancer to lung adenocarcinoma, is still unclear." (PMID 37827692, 2023). "The migration and invasion abilities of lung adenocarcinoma cells were evaluated by comparing the number of cells passing through the Transwell chamber, which demonstrated that MRPL13 knockout significantly reduced the ability of A549 and NCI-H1975 cells to migrate and invade." (PMID 37827692, 2023). "Thus, MRPL13 represents a potential therapeutic target for lung adenocarcinoma and other cancers." (PMID 37827692, 2023). "Furthermore, our research shows that MRPL13 may be an effective therapeutic target for lung adenocarcinoma." (PMID 37827692, 2023). "In lung adenocarcinoma (LUAD), MRPL13 expression was found to be directly proportional to metastasis, epithelial-mesenchymal transition (EMT), the cell cycle, DNA repair, invasion, DNA damage, and proliferation but inversely proportional to hypoxia and inflammation." (PMID 37827692, 2023). "However, there is still a lack of systematic research to explain the significance of MRPL13 in pan-cancer and lung adenocarcinoma." (PMID 37827692, 2023). "The results showed that, compared with normal samples, GMPR was under-expressed in tumors, MRPL13 was overexpressed in lung adenocarcinoma, while the expression of MCFD2 and SALL2 between normal lung tissue and lung adenocarcinoma tissue was not different." (PMID 37946181, 2023).
prostate carcinoma (3 papers, 2021 to 2023). A carcinoma that arises from epithelial cells of the prostate gland. "This analysis strategy revealed the Androgen Receptor (AR) as the top prostate cancer-specific gene hit, but the next four top-ranked hits were genes not previously associated with prostate cancer: KIF4A, MRPL13, NDUFB11, and TSR2 (top 5)." (PMID 34326322, 2021).
non-small cell lung carcinoma (2 papers, 2023). A group of at least three distinct histological types of lung cancer, including non-small cell squamous cell carcinoma, adenocarcinoma, and large cell carcinoma. "In non-small cell lung cancer, the expression of MRPL13 is also higher than that of normal tissues or cells, which can promote the proliferation of tumor cells and induce apoptosis." (PMID 37946181, 2023). "In non-small cell lung cancer, the expression of MRPL13 is also higher than that in normal tissues or cells, promoting tumor cell proliferation and inducing cell apoptosis." (PMID 37946181, 2023). "Additionally, MRPL15, which belongs to the same family as MRPL13, promotes the malignant progression of non-small cell lung cancer and affects the inhibitory effect of the immune system on tumor cells." (PMID 37827692, 2023).
benign ovarian tumors (1 paper, 2025). "Consistent with the IHC and bioinformatics analysis results, MRPL13 mRNA levels were significantly higher in ovarian epithelial malignant tumors than in benign ovarian tumors and normal ovarian tissues." (PMID 40841355, 2025).
lymph node metastasis (1 paper, 2025). "Univariate analysis indicated that MRPL13 expression, FIGO stage, and lymph node metastasis were significantly correlated with survival prognosis." (PMID 40841355, 2025).
ovarian tumor (1 paper, 2025). "In vivo, MRPL13 significantly enhanced ovarian tumor growth." (PMID 40841355, 2025).
thyroid cancer (1 paper, 2025). "Our results showed that both MRPL13 and CLPX are highly associated with the ribosome signaling pathway, while MRPS30 is highly correlated with the thyroid cancer signaling pathway and showed high expression." (PMID 39913623, 2025).
tumor (13 papers, 2019 to 2025). "Within the 8 Mitochondrial-Related Genes (MRGs) analyzed, ACSL1, MTHFD2, and MRPL13 were notably overexpressed in both the high-risk group and tumor tissues." (PMID 38310106, 2024). "The overexpression of DCAF13, EZR, and MRPL13 in patients were associated with lower survival, which reveals that these genes might be associated with tumor invasion, progression and poor prognosis." (PMID 30881302, 2019). "Tumor weight and volume were significantly higher in the MRPL13-overexpression group compared to the control group." (PMID 40841355, 2025). "Subsequently, we extended our in vivo studies by developing a subcutaneous xenograft tumor model in nude mice to further evaluate the role of MRPL13 in OC cell proliferation." (PMID 40841355, 2025). "In this study, we provide evidence that MRPL13 enhances mitochondrial function and promotes tumor progression in OC by inhibiting mPTP opening via SLC25A6." (PMID 40841355, 2025). "Based on our analysis, we identified MRPL13 as a potential regulator of tumor progression in various cancers." (PMID 37827692, 2023). "MHC genes and MRPL13 were coexpressed in almost all tumor types, except TGCT, STAD, STES, LUAD, ESCA, HNSC, and LUSC." (PMID 37827692, 2023). "Our findings are consistent with those of previous studies, further substantiating the positive impact of MRPL13 on tumor cell proliferation and metastasis." (PMID 37827692, 2023). "The results of single-cell sequencing revealed a significant upregulation of MCFD2 and MRPL13 expression in macrophages, vital cellular components in tumor microenvironments." (PMID 37946181, 2023). "Our findings revealed that the expression level of MRPL13 between tumor and normal tissue is significantly different in many cancers." (PMID 37827692, 2023). "MRPL13 overexpression significantly promoted tumor growth and increased tumorigenic capacity." (PMID 40841355, 2025). "Additionally, Ki-67 IHC staining of tumor tissues revealed higher Ki-67 intensity and area in the MRPL13-overexpression group, indicating that MRPL13 accelerates OC cell division and acts as a critical regulator of OC cell proliferation." (PMID 40841355, 2025). "Additionally, the expression of MRPL13 is negatively correlated with hypoxia and inflammation modules, further supporting its role in the tumor microenvironment." (PMID 40371222, 2025). "Our results suggest that MRPL13 may influence genes that regulate tumor progression, which provides insight into the potential role of MRPL13 in cuproptosis and tumor treatment." (PMID 37827692, 2023). "MRPL13, a member of this family, is believed to drive tumor initiation and progression." (PMID 37827692, 2023). "Decreasing MRPL13 expression may therefore be a promising strategy to inhibit tumor initiation and progression." (PMID 37827692, 2023). "In summary, MRPL13 plays a role as a tumor promoter in some cancers, promoting tumor growth, invasion, and drug resistance by affecting the conduction of carcinogenic signaling pathways, the change in the immune microenvironment, and the proliferation of the vascular matrix." (PMID 37827692, 2023). "Finally, to obtain the alterations of MRPL13 and its expression data in pan-cancer, the expression difference of MRPL13 in different samples in each tumor was calculated by R software (version 4.1.3)." (PMID 37827692, 2023). "Overall, MRPL13 is one of the important directions in tumor treatment research." (PMID 37946181, 2023). "MRPL13 can weaken the antitumor immune effect by affecting the tumor immune microenvironment." (PMID 37827692, 2023).
tumor (continued). "Furthermore, the correlation between MRPL13 and the tumor dryness score in pan-cancer showed that MRPL13 was positively correlated with the tumor dryness score in most cancers." (PMID 37827692, 2023). "Overall, MRPL13 is one of the important directions of tumor treatment research." (PMID 37946181, 2023). "Moreover, a few studies have suggested that MRPL13 promotes tumor cell activity." (PMID 37827692, 2023). "Potential signaling mechanisms of MRPL13 involve PI3K, AKT, and mTOR as demonstrated in the regulation of BRCA tumor cell proliferation and migration." (PMID 39913623, 2025). "Knocking down MRPL13 in LUAD significantly reduces cancer cell viability, delays tumor division and migration, diminishes invasive capacity, and promotes apoptosis." (PMID 40371222, 2025). "Knockdown of MRPL13 in LUAD led to decreased cancer cell survival, delayed tumor division and migration, reduced invasion, and increased cancer cell apoptosis." (PMID 37827692, 2023). "MRPL13, along with other highly altered RBPs, has only been shown to interact with ESR2, a tumor suppressor in breast and other cancer types." (PMID 35453681, 2022). "siRNA-mediated knockout of MRPL13 reduces the expression of mitochondrial protein in SNU387 cells, reduces oxygen consumption, and increases CLN1-mediated tumor cell invasiveness." (PMID 34868337, 2021). "Moreover, some studies have found that certain compounds (such as acetaminophen, carbamazepine, and tunicamycin) can exert anti-tumor effects by targeting specific MRPs (such as MRPL12 and MRPL13)." (PMID 40371222, 2025). "Likewise, an additional study found increased MRPL13 mRNA and protein expression in NSCLC tumours compared to normal tissue, with the highest expression observed in a metastatic NSCLC cell line (H1299)." (PMID 39354291, 2024).
cancer (12 papers, 2021 to 2025). A tumor composed of atypical neoplastic, often pleomorphic cells that invade other tissues. "(2023) found that by employing MRPL13 as a diagnostic biomarker, the accuracy of diagnostic predictions across multiple cancer types, including LUAD, were improved, which is a promising area of future research." (PMID 39354291, 2024). "Subsequently, we conducted an analysis of the patient prognosis across four types of cancer based on mutation groups, revealing a poor prognosis for patients in the MRPL13 mutation group in STAD." (PMID 37827692, 2023). "Several studies have indicated that MRPL13 is associated with the proliferation cycle, migration ability, apoptosis and autophagy of cancer cells." (PMID 37827692, 2023). "Our study showed that MRPL13 and its associated genes were significantly correlated with cuproptosis-related genes across cancers, with the most significant ones being FDX1, GCSH, DLST, and DLD." (PMID 37827692, 2023). "Single-cell data further confirmed the positive association between MRPL13 expression and various cancer cell states, including the cell cycle, invasion, metastasis, and proliferation." (PMID 37827692, 2023). "Evaluation of the receiver operating characteristic (ROC) curve confirmed the diagnostic value of MRPL13 across cancers." (PMID 37827692, 2023). "Furthermore, immune-stimulating factors and immunosuppressive factors were closely associated with the expression of MRPL13 across cancers." (PMID 37827692, 2023). "MRPL13 mutation and gene expression significantly affect many cancer types." (PMID 37827692, 2023). "We investigated the changes in the functional status of 14 cancers caused by MRPL13." (PMID 37827692, 2023). "Analyzing the ROC curve of 13 cancers with differential MRPL13 expression obtained from the TCGA analysis of matched and unmatched samples, we found that the diagnostic accuracy of the AUC analyzed by this model was high in 9 cancers, relatively high in 1 cancer, and low in 2 cancers." (PMID 37827692, 2023). "Although the relationship between mitochondrial dysfunction and cancer transformation is increasingly understood, the role of MRPL13 in regulating mitochondrial function and OC progression has remained unclear." (PMID 40841355, 2025). "For example, MRPL13 is closely related to immune cell infiltration in various cancers, with its high expression negatively correlated with the infiltration of M1 macrophages, CD8+ T cells, and CD4+ T cells." (PMID 40371222, 2025). "Specifically, a TCGA Pan-Cancer Atlas analysis revealed that MRPL13 is significantly upregulated in LUAD patient samples." (PMID 39354291, 2024). "This study also found an association between MRPL13 expression and MYC, PI3K/AKT/mTOR, metabolism, cell cycle pathways, and increased proliferation, suggesting links to cancer progression and potentially EMT promotion." (PMID 39354291, 2024). "The results demonstrate a strong positive correlation between MRPL13 and most genes involved in modifying RNA methylation in some types of cancer, including ACC, KICH, BRCA, LUAD, and STAD." (PMID 37827692, 2023). "In conclusion, this study provides the first comprehensive analysis of the role of MRPL13 in pan-cancer development." (PMID 37827692, 2023). "In summary, we used a combination of bioinformatics and experimental applications to study the potential roles of MRPL13 in cancer." (PMID 37827692, 2023). "Using TIMER, QUANTISEQ, and XCELL, we mapped the MRPL13 gene expression of pan-cancer patients in the TCGA dataset to the corresponding immune cell infiltration and constructed a correlation heatmap." (PMID 37827692, 2023). "Subsequently, we analyzed the correlation between FOXM1 and MRPL13 across various cancers and created a correlation map." (PMID 37827692, 2023). "The results indicated that MRPL13 and most immune-related genes had the same change trend in specific cancer types." (PMID 37827692, 2023).
cancer (continued). "We analyzed the sequencing data of BRCA, LUAD, HNSC, and STAD in TCGA using R language, and the genes related to the expression of MRPL13 in each cancer were identified." (PMID 37827692, 2023). "In general, MRPL13 acts as a potential marker of genomic stability in a variety of cancer species, including LUAD, and affects patient prognosis and therapeutic responses." (PMID 37827692, 2023). "By downloading the single-cell sequencing data from the CancerSEA database and using Xiantao Academic’s online mapping service, we explained the influence of MRPL13 on the functional status of 14 kinds of cancers." (PMID 37827692, 2023). "This study is the first to report a correlation between MRPL13 and cancer prognosis across multiple cancer types." (PMID 37827692, 2023). "The evaluation of the ROC curve demonstrated that MRPL13 is highly valuable in diagnosing pan-cancer, including LUAD, and underscores its significance in aiding the diagnosis and treatment of clinical patients." (PMID 37827692, 2023). "In particular, chemokines, including CXCL8, CXCL10, CXCL11, CXCL16, CCL26, and CCL7, as well as chemokine receptors, including CXCR3, CCR2, CCR5, and CCR1, were positively correlated with MRPL13 expression in various cancer types." (PMID 37827692, 2023). "MRPL13 is involved in regulating cancer through potential pathways such as the MYC target, oxidative phosphorylation, PI3K/AKT/mTOR signal transduction, and the G2/M checkpoint." (PMID 37827692, 2023). "Nonetheless, further research is necessary to investigate the molecular pathways and functions of MRPL13 in cancer." (PMID 37827692, 2023). "The comprehensive evaluation score of MRPL13 protein was significantly different between the cancer tissue group and adjacent normal tissue group." (PMID 37827692, 2023). "The expression data (UCSC database) of MRPL13 and 44 marker genes of three RNA modification genes in each sample of the pan cancer dataset were extracted and converted by formula." (PMID 37827692, 2023). "Almost all cancers showed a significant relationship between MRPL13 and immune checkpoint suppressor genes, such as VEGFA, CD274 (PD-L1), and CTLA4." (PMID 37827692, 2023). "By downloading the single-cell data in the CancerSEA database and uploading the data to Xiantao Academic to draw a correlation map, it was found that the expression of MRPL13 is significantly related to the cell cycle in most cancers." (PMID 37827692, 2023). "We compared the correlation of TMB, MSI, HRD, and PLOIDY with MRPL13 across various cancer types." (PMID 37827692, 2023). "In most cancers, MRPL13 is directly proportional to most cell cycle-related marker genes." (PMID 37827692, 2023). "Moreover, through quantitative experiments, we observed higher expression of MRPL13 in cancer tissues at the RNA or protein level." (PMID 37827692, 2023). "MSI analysis showed that MRPL13 had a significant positive correlation with eight types of cancers." (PMID 37827692, 2023). "Furthermore, MRPL13 is closely related to the cancer cell cycle, RNA processing (degradation/splicing) and the M-TORC1 pathway." (PMID 37827692, 2023). "The enrichment analysis of biological processes indicates that MRPL13 may regulate mitotic cell cycle phase transition, cell cycle regulation, and DNA replication across cancers." (PMID 37827692, 2023). "Additionally, our analysis of TCGA data indicated that MRPL13 expression is a prognostic indicator for several cancer types, including LUAD, BRCA, HNSC, and STAD." (PMID 37827692, 2023). "Among CML and LUAD, MRPL13 is most closely related to all fourteen cancer functional states." (PMID 37827692, 2023). "Furthermore, we studied the relationship between the expression level of MRPL13 across cancers and the change in cancer functional status through single-cell data." (PMID 37827692, 2023).